SAP18 (Sin3A associated protein 18)
Description:
Component of the SIN3-repressing complex. Enhances the ability of SIN3-HDAC1-mediated transcriptional repression. When tethered to the promoter, it can direct the formation of a repressive complex to core histone proteins. Auxiliary component of the splicing-dependent multiprotein exon junction complex (EJC) deposited at splice junction on mRNAs. The EJC is a dynamic structure consisting of core proteins and several peripheral nuclear and cytoplasmic associated factors that join the complex only transiently either during EJC assembly or during subsequent mRNA metabolism. Component of the ASAP and PSAP complexes which bind RNA in a sequence-independent manner and are proposed to be recruited to the EJC prior to or during the splicing process and to regulate specific excision of introns in specific transcription subsets. The ASAP complex can inhibit mRNA processing during in vitro splicing reactions. The ASAP complex promotes apoptosis and is disassembled after induction of apoptosis. Involved in the splicing modulation of BCL2L1/Bcl-X (and probably other apoptotic genes); specifically inhibits the formation of proapoptotic isoforms such as Bcl-X(S); the activity is different from the established EJC assembly and function.
Synonyms: SAP18p; 2HOR0202; MGC27131
Tractability: Small molecule: it has a binding pocket of medium quality. PROTAC: UniProt records ubiquitination sites on it; ubiquitination databases record sites on it; its protein half-life has been measured.
Gene: Protein-coding gene on chromosome 13 (21,140,119 to 21,149,097, forward strand). Ensembl gene ENSG00000150459.
Subcellular location: Nucleus; Cytoplasm; Nucleus speckle
Subcellular location (Human Protein Atlas): Nuclear bodies; Nucleoplasm; Cytosol
Pathways (Reactome):
Chromatin organization: HDACs deacetylate histones
Disease: Potential therapeutics for SARS
Gene expression (Transcription): NoRC negatively regulates rRNA expression
Metabolism of RNA: mRNA Splicing - Major Pathway
Gene Ontology:
Molecular function: protein binding; RNA binding; transcription corepressor activity
Biological process: negative regulation of mRNA splicing, via spliceosome; positive regulation of apoptotic process; regulation of alternative mRNA splicing, via spliceosome; regulation of mRNA processing; negative regulation of DNA-templated transcription; regulation of transcription by RNA polymerase II
Cellular component: ASAP complex; cytoplasm; cytosol; exon-exon junction complex; nuclear body; nuclear speck; nucleoplasm; nucleus; histone deacetylase complex
Genetic constraint (gnomAD): Loss-of-function variants: 4 observed, 14.57 expected, observed/expected ratio (o/e) 0.27, 90% interval 0.13 to 0.63. The synonymous counts are far from expectation, so gnomAD's model fits this gene poorly and the ratio says little. Missense variants: 168 observed, 227.11 expected, observed/expected ratio (o/e) 0.74, 90% interval 0.65 to 0.84. Synonymous variants: 112 observed, 86.19 expected, observed/expected ratio (o/e) 1.3, 90% interval 1.11 to 1.52.
Homologues: Orthologues: chimpanzee SAP18 (100% identical), macaque SAP18 (100% identical), guinea pig SAP18 (98% identical), pig SAP18 (98% identical), mouse Sap18 (98% identical), mouse Sap18b (98% identical), rat Sap18 (98% identical), dog SAP18 (88% identical), tropical clawed frog sap18 (84% identical), zebrafish sap18 (80% identical), Drosophila melanogaster Bin1 (47% identical), Caenorhabditis elegans C16C10.4 (43% identical).
Diseases named in the same sentence as SAP18 in open-access papers:
SAP18 is named in the same sentence as 19 diseases in open-access papers, as found by Europe PMC text mining. Sharing a sentence is not in itself a finding about the gene and the disease. The quoted sentences say what the papers report.
breast carcinoma (1 paper, 2020). "For example, A671 had no inhibitory effect on cell growth or SAP18 mRNA or protein expression in the breast cancer cell lines MDA-MB-231 and 4T1." (PMID 33273692, 2020).
breast tumors (1 paper, 2023). "SIN3B, HDAC1, HDAC2, SUDS3, and RBBP4, but not SIN3A and SAP18, were also upregulated to a lesser degree in human breast tumors." (PMID 37655663, 2023).
erythroleukemia (1 paper, 2020). Acute erythroid leukemia characterised by the presence of at least 50% erythroid precursors and at least 20% myeloblasts in the bone marrow. "The SAP18 agonist compound, A671, with potent inhibitory effect against T-cell lymphoma and erythroleukemia through SIRT3 downregulation needs further investigation for the treatment of these, and other malignancies in which the SAP18/SIRT3 regulatory axis is intact." (PMID 33273692, 2020).
HIV-1 infection (1 paper, 2009). The type species of lentivirus and the etiologic agent of acquired immunodeficiency syndrome (AIDS). "Since both IN and INI1 bind to SAP18, it is possible that association of INI1 with SAP18-Sin3a-HDAC1 complex is increased upon HIV-1 infection." (PMID 19503603, 2009).
Kaposi's sarcoma (1 paper, 2022). A malignant neoplasm characterized by a vascular proliferation which usually contains blunt endothelial cells. "For example, in Kaposi's sarcoma, vFLIP was found to degrade SAP18 through the ubiquitin–proteasome pathway by recruiting the E3 ubiquitin ligase TRIM56." (PMID 36471347, 2022).
squamous cell carcinoma (1 paper, 2020). A carcinoma arising from squamous epithelial cells. "Subsequently, it was shown that S385 DNp63a phosphorylation is induced by cisplatin in squamous cell carcinoma cells, leading to RNA splicing and ACIN1-mediated cell death via interaction with spliceosome components SAP18, RBM38, ELAVL, SRPK2, SRSF2, and ACIN1." (PMID 33375680, 2020).
T-cell leukemia (1 paper, 2020). A malignant disease of the T-lymphocytes in the bone marrow, thymus, and/or blood. "Here, we identified a unique HDACi that possessed a potent anti-T cell leukemia activity by direct binding to and stabilization of SAP18, leading to downregulation of SIRT3 transcription through activation of the SAP18/SIN3 suppressor complex, resulting in apoptotic cell death." (PMID 33273692, 2020).
tumor (6 papers, 2019 to 2023). "CXCR2 deficiency increased SAP18 expression in tumor-bearing mice, which reduced STAT3 phosphorylation through restraining ERK1/2 activation." (PMID 31395859, 2019). "While SAP18 expression induced in A671 sensitive tumor cells, its transcript and protein levels remained unchanged in drug-resistant cells." (PMID 33273692, 2020). "The results showed that knocking down SAP18 in CXCR2−/− tumor-bearing mice increased the percentage of mo-MDSCs, and the level of Pu.1 and Egr1 mRNA was also recovered." (PMID 31395859, 2019). "Immunoblot analyses showed that the knock down of SAP18 was evident in the HSPCs of CXCR2−/− tumor-bearing mice." (PMID 31395859, 2019). "Immunoblot analyses showed that ERK1/2 phosphorylation was markedly decreased in the WT tumor-bearing mice over-expressing SAP18 and increased in CXCR2−/− tumor-bearing mice treated with the SAP18 knock down." (PMID 31395859, 2019). "Our findings reveal a critical role for CXCR2 in regulating hematopoietic progenitor cell differentiation under tumor conditions, and SAP18 is a key negative regulator in this process." (PMID 31395859, 2019). "Treatment with anti-mSin3A Abs enriched the same DNA fragments which had been enriched by the anti-SAP18 Abs, and the enrichment by the anti-mSin3A Abs was enhanced when SAP18 was overexpressed in WT tumor-bearing mice." (PMID 31395859, 2019). "The increased binds of CXCL1 or CXCL2 to CXCR2 leads to reduced SAP18 expression under tumor conditions, which subsequently activates the ERK/STAT3 signaling pathway to promote mo-MDSCs accumulation." (PMID 31395859, 2019). "Immunoblot analyses further showed that the knockdown of SAP18 in CXCR2−/− tumor-bearing mice resulted in a substantial increase in HRAS and PI3Kγ expression." (PMID 31395859, 2019). "SAP18 has been shown to modulate neutrophil migration and autophagy in tumor microenvironment; meanwhile neutrophil autophagy is highly related to the development of tumor." (PMID 35812454, 2022). "Furthermore, SAP18 expression was found to be up-regulated in hematopoietic stem cells and their progenitor cells (HSPCs) of CXCR2-deficient tumor-bearing mice." (PMID 31395859, 2019). "In addition, SAP18 overexpression in WT tumor-bearing mice markedly decreased the expression of HRAS and PI3Kγ and the expression of HRAS and PI3Kγ was closely connected with ERK1/2 activation." (PMID 31395859, 2019). "Furthermore, we found that there was a reverse trend of ERK-mediated STAT3 activation in response to the alteration of SAP18 expression under tumor conditions." (PMID 31395859, 2019). "Our results showed that SAP18 expression was not affected by a CXCR2 deficiency in normal mice; however, SAP18 expression was increased when CXCR2 was deficient under tumor conditions." (PMID 31395859, 2019). "Moreover, enrichment with the anti-SAP18 Abs was enhanced in CXCR2−/− tumor-bearing mice." (PMID 31395859, 2019). "Thus, the ability of A671 to stabilize SAP18 and to block SIRT3 expression is a potential biomarker of tumor responsiveness to the drug." (PMID 33273692, 2020).
cancer (1 paper, 2020). A tumor composed of atypical neoplastic, often pleomorphic cells that invade other tissues. "The resistance of cancer cells to A671 correlated with diminished SAP18 activation and sustained SIRT3 expression." (PMID 33273692, 2020). "As noted, the effect of A671 on SAP18 and SIRT3 was cancer-specific." (PMID 33273692, 2020). "A search of the DepMap CRISPR database of gene knockout for SIRT3/SAP18/SIN3 across hundreds of cancer cell lines identified SAP18/SIN3 but not SIRT3 as a critical survival gene." (PMID 33273692, 2020). "The impact of these compounds on SAP18 stability and the SAP18/SIRT3 ratio may serve as indicators for survival and drug response in other cancer types." (PMID 33273692, 2020). "Since the binding of A671 to SAP18 is critical for its effects, it is possible that this compound–target interaction not accessible in drug-resistant cancer cell lines." (PMID 33273692, 2020). "So far, a connection between SIN3/SAP18 and SIRT3 not been established, nor is it known if such interaction impacts cancer and whether it exploited therapeutically." (PMID 33273692, 2020).
infection (1 paper, 2009). The state of being infected such as from the introduction of a foreign agent such as serum, vaccine, antigenic substance or organism. "By binding to INI1 and SAP18, HIV-1 IN may inhibit anti-viral interferon response during infection." (PMID 19503603, 2009).
SAP18 also shares sentences with these, for which no sentence is quoted: acute lymphoblastic leukemia (1 paper); Alzheimer disease (1); Down syndrome (1); epithelial ovarian cancer (1); Hepatic steatosis (1); papillary renal cell carcinoma (1); papillary thyroid cancer (1); T-cell acute lymphoblastic leukemia (1); T-cell lymphoma (1).